NEAT1 (nuclear paraspeckle assembly transcript 1)
Diseases named in the same sentence as NEAT1 in open-access papers (continued):
Sharing a sentence is not in itself a finding about the gene and the disease.
hematological malignancies (4 papers, 2020 to 2024). "Numerous studies have demonstrated that dysregulation of NEAT1 is closely related to the progression of hematological malignancies." (PMID 34354942, 2021). "In concert with MALAT1, also NEAT1 is emerging as a novel biomarker and crucial regulator in the pathogenesis of several human tumors although with distinct roles in solid tumors versus hematological malignancies." (PMID 33193626, 2020).
metabolic disease (4 papers, 2021 to 2026). A congenital disorder (due to inherited enzyme abnormality) or acquired (due to failure of a metabolically important organ) disorder resulting from an abnormal metabolic process. "NEAT1 exacerbates metabolic disorders in PCOS mice by downregulating miR-324-3p and upregulating BRD3." (PMID 39334761, 2024). "In the lncRNA-miRNA-mRNA network, NEAT1 regulates CAPG/DDAH2 through miR-1179/miR-1276, which is consistent with previously reported pivotal roles of NEAT1 in inflammation and metabolic diseases." (PMID 41050938, 2025).
inflammation (2 papers, 2019 to 2022). Aberrant reaction of the microcirculation characterized by movement of fluid and leukocytes from the blood into extravascular tissues. "The overt defects of Neat1−/− mice in alum-induced peritoneal inflammation and flagellin-induced lung inflammation emphasize an important function for Neat1 in the activations of the canonical inflammasomes, the subsequent accumulation of immune cells and the associated symptoms in vivo." (PMID 30940803, 2019). "Furthermore, LncRNA NEAT1 plays a crucial role in several inflammation diseases." (PMID 35034548, 2022).
cardiac diseases (1 paper, 2023). "Several studies have shown that lncRNA nuclear paraspeckle assembly transcript 1 (NEAT1) plays an important role in cardiac diseases." (PMID 37759491, 2023).
digestive system cancer (1 paper, 2017). A primary or metastatic malignant neoplasm involving any part of the digestive system. "The overall AUC of NEAT1 in digestive system cancers was 0.72 (95%CI: 0.65-0.80), and the diagnostic sensitivity and specificity were 0.67 and 0.83, respectively." (PMID 28118609, 2017). "It is worth mentioning that there is no systematic report on the expression level and diagnostic role of NEAT1 in digestive system cancers." (PMID 28118609, 2017). "To further evaluate the diagnostic value of NEAT1 in digestive system carcinomas, we generated summary receiver operating characteristic (SROC) curves and then calculated the area under the curve (AUC) with the diagnostic sensitivity and specificity." (PMID 28118609, 2017). "Our study suggests that NEAT1 may play different roles in the initiation and progression of digestive system cancers and could be a potential diagnostic and prognostic biomarker in patients with digestive system carcinomas." (PMID 28118609, 2017). "According to our study, NEAT1 may play different roles in the initiation and progression of digestive system cancers." (PMID 28118609, 2017). "Thus more reports on the prognostic role of NEAT1 in different types of digestive system cancers are necessary to validate our conclusion." (PMID 28118609, 2017). "We hypothesize that NEAT1 is involved in the occurrence and progression of digestive system cancers through ceRNA regulation networks." (PMID 28118609, 2017). "In summary, according to our results, NEAT1 might play different roles in the initiation and progression of digestive system cancers." (PMID 28118609, 2017). "Our findings suggested that NEAT1 may have different expression patterns and play diverse roles in the initiation and development of different digestive system cancers." (PMID 28118609, 2017). "However, the diagnostic performance of NEAT1 in other digestive system cancers has not yet been reported." (PMID 28118609, 2017). "However, the exact molecular mechanism of NEAT1 in tumorigenesis and the development of digestive system carcinomas remain unclear and needs to be explored further." (PMID 28118609, 2017). "However, the prognostic value of NEAT1 in patients with digestive system carcinomas had not been presented separately." (PMID 28118609, 2017).
hematologic cancers (1 paper, 2017). "Yet, there was no study that spotlighted Neat1 and focused on its role in paraspeckle formation in hematologic cancers." (PMID 29312630, 2017).
infectious disease (1 paper, 2024). A disorder directly resulting from the presence and activity of a microbial, viral, or parasitic agent in humans. "Some of these lncRNAs, such as NEAT1, MALAT1, and UGDH-AS1 have been reported to regulate the pathophysiology and outcomes in other infectious diseases (such as influenza A virus, dengue virus, human immunodeficiency virus) as well." (PMID 38770134, 2024). "Therefore, it is imperative to look into the lncRNA-specific functional importance of RNA editing events, especially since both NEAT1 and UGDH-AS1, the two lncRNAs with high editing frequency, are reported to be involved in multiple infectious diseases." (PMID 38770134, 2024).
skin disorder (1 paper, 2021). Any deviation from the normal structure or function of the skin or subcutaneous tissue that is manifested by a characteristic set of symptoms and signs. "Therefore, NEAT1 knockdown may suppress the development of skin disorders." (PMID 34414852, 2021).
NEAT1 also shares sentences with these, for which no sentence is quoted: chronic lymphocytic leukemia (5 papers); laryngeal squamous cell carcinoma (5); oral squamous cell carcinoma (5); Encephalopathy (4); Parkinson's (4); kidney clear cell carcinoma (3); myeloid leukemia (3); neuropathic pain (3); peritonitis (3); renal carcinoma (3); acute myocardial infarction (2); allergic disease (2); aortic aneurysm (2); atrial fibrillation (2); cardiomyopathies (2); endometrial endometrioid adenocarcinoma (2); Fibroadenoma (2); hepatoblastoma (2); Liver Cirrhosis (2); memory impairment (2); metastasis (2); paraganglioma (2); pheochromocytoma (2); Spinal Tuberculosis (2); stomach cancer (2); tongue squamous cell carcinoma (2); type 1 diabetes (2); viral diseases (2); acute liver failure (1); acute lung injury (1).
A further 79 diseases each share a sentence with NEAT1 in 1 paper.